LEP (leptin)
Diseases named in the same sentence as LEP in open-access papers (continued):
Sharing a sentence is not in itself a finding about the gene and the disease.
Obesity (continued). "From the literature, it is already known that the ratio between leptin and adiponectin is an important parameter that can be used to indicate the risk of developing obesity and even metabolic syndrome." (PMID 31146419, 2019). "Linear correlation was observed between weight loss and the leptin levels in rodents and humans as reduced leptin sensitivity leads to obesity and causes a compensatory increase in plasma leptin levels." (PMID 31488172, 2019). "Congenital leptin deficiency (CLD) is a rare human genetic disorder caused by homozygous mutations of the LEP gene resulting in severe hyperphagia and early-onset obesity." (PMID 31067764, 2019). "Leptin resistance is either a condition induced by human obesity or a natural phenomenon associated with seasonality in ruminants." (PMID 31780867, 2019). "In searching the GEO (Gene Expression Omnibus) database, we found that miR-451 was downregulated in patients with alcoholic hepatitis (AH), HCV-induced cirrhosis (HVC-CH), alcohol liver disease-induced cirrhosis (ALD-CH), and leptin-deficient obesity mice." (PMID 31816816, 2019). "Although this LEP SNP located in non-coding exon, but it was found to be associated with severe obesity and increase leptin levels due to its critical position in 5′UTR regulatory region." (PMID 32042833, 2019). "Using a mouse model of obesity (ob/ob), the present study investigated if estradiol and leptin associate with longitudinal changes in gut microbiota and energy homeostasis in female mice on a HFD." (PMID 31882890, 2019). "Taken together, these results suggest that higher serum leptin concentration and free leptin index, as well as lower serum sOBR and kisspeptin concentrations, are significantly associated with obesity in postmenopausal women." (PMID 31871451, 2019). "Loss of leptin (ob/ob) or the Lep-R mutation (db/db) causes a series of metabolic abnormalities in mice, including obesity, diabetes, and hypercorticoidemia." (PMID 31022919, 2019). "The JAK/STAT pathway is implicated in obesity and chronic metabolic diseases, serving as an important adjuster for growth factor hormones and cytokines of leptin, IL-6, and IFN-γ." (PMID 31344867, 2019). "The second study was designed as a case control and confirmed the association of the N103K mutation with early obesity in a 10-year-old Pakistani patient who also had a very low serum Leptin level, suggestive of a functional impact of the mutation." (PMID 31871931, 2019). "Another study on HFD female DBA/2J mice proposed that obesity-linked hyperleptinemia, slowly prompted central leptin resistance, amplified hypothalamic neuropeptide Y transmission and eventually led to hypothalamic hypogonadism." (PMID 32082253, 2019). "Based on our current analysis, it is likely that the childhood sleeping time acts as a long term modifier on the effect of polygenic risk for obesity through the leptin pathway." (PMID 31285522, 2019). "In our cohort, some of the obesity-related genes were associated with leptin, an adipocytokine; CRP, an inflammatory marker; and FMD%, an index of endothelial function." (PMID 31466225, 2019). "Meanwhile, both the direct and indirect effects were attenuated with the increase in sleep duration, with the finding indicating that sleep duration modified the polygenic obesity risk mainly via the leptin pathway to impact 10-year follow-up BMI." (PMID 31285522, 2019). "A treatable form of monogenic obesity is due to homozygous mutations in the LEP gene leading to recessively inherited congenital leptin deficiency." (PMID 31067764, 2019). "Obesity is thought to be associated with leptin resistance, questioning the relevance of our findings in obesity." (PMID 30676227, 2019). "The leptin-deficient ob/ob mouse is a key animal model for the investigation of obesity and type 2 diabetes." (PMID 31109074, 2019).
Obesity (continued). "This study aimed to explore wherethe most variable region is in leptin gene and analyse microsatellite repeats with direct sequencing in Iraqis and compare our alleles with other populations as a risk for obesity and T2D predisposition." (PMID 32042833, 2019). "In our study, the leptin level was significantly higher in group M, suggesting leptin resistance, which is associated with diet-induced obesity." (PMID 31117266, 2019). "The increased leptin-adiponectin ratio seen in obesity has been implicated in neoplastic transformation and tumor progression." (PMID 30823902, 2019). "Other than known syndromes associated with obesity, there are multiple monogenic forms of obesity which include LEP, LEPR, MC4R, and POMC1 majorly." (PMID 31070016, 2019). "Although both were associated with salivary CRP, insulin, and adiponectin, leptin was unique for obesity evaluated by waist circumference." (PMID 31236292, 2019). "It is well established that obesity is associated with dysregulation of the ratio between the two major adipokines leptin and adiponectin." (PMID 30732639, 2019). "For example, in a longitudinal study conducted on obese Pima Indians, participants who gained weight had lower mean plasma LEP levels compared to those with a stable weight, suggesting the positive association of low LEP levels with weight gain and obesity." (PMID 31878053, 2019). "Recent studies have demonstrated that a number of adipokines (adiponectin, vaspin, leptin, chemerin, etc.)have been associated with inflammatory responses and metabolic disorders in patients with obesity." (PMID 31772689, 2019). "Further, depletion of resistin in leptin-deficient (ob/ob) and diet-induced obesity mice improved hepatic glucose production and increased peripheral glucose uptake." (PMID 31208019, 2019). "Leptin is involved in food intake and energy balance, and genetic mutations in the leptin pathway can cause obesity in humans and rodents." (PMID 31828124, 2019). "Altered plasma leptin levels and the leptin-resistant state associated with obesity has been shown to be associated with impaired trophoblastic invasion and early miscarriage." (PMID 31823750, 2019). "Apart from the coexistence of autoimmune thyroiditis, which are highly prevalent in the general population, a neuroendocrine dysfunction mediated by the adipocyte derived leptin has been postulated as a cause of elevated TSH levels in obesity." (PMID 31151171, 2019). "For example, leptin-deficient ob/ob mice are one of the most investigated mice models of obesity that represent morbid obesity, insulin resistance, hyperphagia, and infertility." (PMID 31828124, 2019). "Recently, several researchers have explored genetic and epigenetic processes including single nucleotide polymorphism (SNP), methylation, and expression of LEP in obesity and OA." (PMID 31878053, 2019). "In summary, we demonstrate that celastrol improves leptin sensitivity and ameliorates age‐associated obesity in mice." (PMID 30821426, 2019). "Adiponectin, in sharp contrast to leptin, plasma Ad levels are negatively correlated with body fat, decreasing with obesity and increasing with weight loss." (PMID 31191339, 2019). "Hypogonadism associated with obesity is not only associated with low testosterone, but also high estrogen, high insulin, leptin resistance among other hormonal abnormalities." (PMID 31052376, 2019). "Circulating leptin is one of the factors involved in the association between obesity and some solid cancers." (PMID 31817072, 2019). "Another endometriosis-related gene, LEP, functions as a key mediator in obesity-associated cancers including breast, colorectal and prostrate (Renehan, Soerjomataram & Leitzmann, 2010)." (PMID 31879572, 2019). "It has been found that obesity increases the risk of having autoimmune thyroid diseases with an emerging role for leptin in thyroid autoimmunity." (PMID 31157131, 2019).
Obesity (continued). "Ob/ob mice, which are hyperphagic due to leptin deficiency, are commonly used models of obesity and were instrumental in suggesting links between gut microbiota and obesity." (PMID 33499919, 2019). "Previous studies have demonstrated that natural loss-of-function mutations in the SH2B1 gene in humans lead to both elevated food intake and severe obesity associated with leptin resistance." (PMID 31341224, 2019). "Later exceptionally rare cases of human obesity with mutations in the genes coding for leptin or its receptor were described." (PMID 31656948, 2019). "In conclusion, only obesity was significantly associated with LEP promoter methylation (higher levels) specifically in osteoarthritic patients." (PMID 31878053, 2019). "Since leptin resistance is implicated in the pathogenesis of obesity, we herein report the effects of laparoscopic sleeve gastrectomy (LSG) on the serum levels of leptin and leptin receptor, in addition to its overall effect on leptin resistance." (PMID 31557979, 2019). "Most of the causative proteins in monogenic forms of obesity are acting in the hypothalamic leptin-melanocortin signalling pathway, which is essential for the regulation of food intake, body weight and energy regulation." (PMID 31488071, 2019). "The primary role of leptin is the control of appetite, mutations in the leptin gene, or leptin receptor gene develop obesity." (PMID 31456748, 2019). "Other studies linked irisin levels with BMI, obesity, and leptin, where obese children who had undergone a physical activity program showed a significant increase in levels of irisin and leptin." (PMID 31065382, 2019). "Leptin is a potent appetite inhibitor, and defects to its protein has been linked to development of obesity." (PMID 31117266, 2019). "Is it possible that a significant subset of patients with obesity and relatively low leptin levels have a state of partial “leptin deficiency” and be responsive to leptin administration?" (PMID 30357355, 2019). "Sleep deprivation can promote the secretion of ghrelin and reduce leptin secretion, which are both associated with obesity." (PMID 31484289, 2019). "Mutations in LEP, the gene encoding leptin, led to altered metabolism and the development of obesity." (PMID 31783495, 2019). "The strict association between obesity and hematopoietic disruption evidenced the role of leptin on bone organization." (PMID 31091785, 2019). "Reducing thrombin action was found to directly improve insulin sensitivity in leptin resistant obese mice, suggesting a causal role for prothrombrotic processes in obesity-related insulin resistance." (PMID 30874564, 2019). "Resistance to the anorexigenic actions of leptin is one of the hallmarks of obesity and is strongly associated with T2D." (PMID 31340540, 2019). "Given the fact that dysfunctional leptin signaling is highly associated with metabolic diseases, such as obesity and T2DM, we therefore adopted C57 BL/KS db/db male mice as a T2DM murine model." (PMID 31760385, 2019). "The association of leptin and leptin receptor mutations with obesity has also been reported in humans." (PMID 31447640, 2019). "Future research efforts should thus perhaps be shifted away from leptin transport across the BBB and focused on other possible causes of leptin resistance, which, if corrected has the potential to have a large impact on the treatment of obesity." (PMID 30283080, 2019). "Mutations in the mouse leptin gene lead to severe obesity and, in nearly all cases, very low plasma leptin concentration." (PMID 31067764, 2019). "With the exception of leptin deficiency due to leptin gene mutations, treatment options are limited in early-onset severe obesity." (PMID 30991789, 2019). "Leptin treatment is corrective in animal models of diabetes and leptin polymorphisms have been linked to obesity in humans." (PMID 31661517, 2019).
Obesity (continued). "Inflammatory responses mediated by TNF-α signaling in the hypothalamus are integrally involved in obesity in genetical leptin–deficient obese models." (PMID 31739649, 2019). "Regarding the relationship between obesity and the inflammatory and iron markers, pgBMI was positively associated to IL-6, leptin, and CRP." (PMID 30909605, 2019). "First described in humans in 1997, congenital leptin deficiency is associated with early-onset severe obesity, hyperphagia, lower energy expenditure, impaired satiety, and low leptin levels." (PMID 32010059, 2019). "To investigate the mechanism underlying celastrol’s anti-obesity and leptin-sensitizing effects, we explored how hypothalamic gene expression is affected by celastrol." (PMID 31488870, 2019). "Relieving hypothalamic neuronal endoplasmic reticulum (ER) stress with the natural small molecule drugs celastrol or withaferin-A reverses the leptin resistance commensurate with obesity, producing a degree of weight loss found only with bariatric surgery." (PMID 31225498, 2019). "Our previous cross-sectional study confirmed similar study-wide significant association with the baseline BMI and obesity for the polygene score consisting of all the 12 adult BMI loci (GPSall) and the GPSleptin of 6 leptin-related loci." (PMID 31285522, 2019). "We therefore evaluated GIP secretion in leptin-deficient Lepob/ob mice, which develop severe obesity under the normal chow diet." (PMID 31509948, 2019). "Leptin constitutes a relevant hormonal “actor” in obesity, immune-system homeostasis and in several associated metabolic-related as well as immune-mediated diseases." (PMID 31091785, 2019). "The excess intake of energy from food is a primary cause for the development of obesity both in rodents and humans, and leptin plays a central role in this regulation." (PMID 31509948, 2019). "Leptin replacement normalises these hormonal and metabolic alterations, suggesting that leptin deficiency or inactivity is the predominant determinant of obesity associated disorders in these patients." (PMID 29217499, 2018). "And in a genetic model of obesity, the leptin-deficient Ob/Ob mouse, ARC Kiss1 mRNA levels are reduced or unchanged as compared to control mice." (PMID 29740399, 2018). "The increase in circulating leptin that occurs in association with obesity has been suggested to act as a signal that an adequate nutritional status exists for puberty to occur, allowing activation of central mechanisms." (PMID 29706935, 2018). "Some studies have reported that obesity is positively associated with high bone mass probably as a result of the increased levels of hormones such as leptin, insulin, and estrogen that are known to induce bone growth and inhibit the bone remodeling process." (PMID 30327744, 2018). "Early work with mouse models implicated leptin and its cognate receptor as implicated in monogenic obesity." (PMID 30121879, 2018). "This review discusses the latest data regarding the role of leptin as a mediator of immune system and metabolism, with particular emphasis on its effects on obesity-associated metabolic disorders and autoimmune and/or inflammatory rheumatic diseases." (PMID 29910742, 2018). "This study investigated the potential role of candidate gene variants of leptin and adiponectin in sex-specific pathways of obesity and colorectal carcinogenesis." (PMID 30379922, 2018). "Mutations in the ob gene (which encodes leptin) or the leptin receptor gene lead to severe obesity in humans and rodents mainly due to hyperphagia." (PMID 30423881, 2018). "Associations of candidate leptin variants with colorectal cancer among post-menopausal women, by obesity status." (PMID 30379922, 2018). "Clinical evidence has revealed a significantly greater risk of developing AD in individuals with midlife obesity, suggesting that impaired leptin function or leptin resistance contributes to the incidence of AD." (PMID 29860205, 2018).
Obesity (continued). "Leptin is a hormone linked to fat stores and diseases such as anorexia nervosa, obesity, and Alzheimer's." (PMID 29851973, 2018). "It has been demonstrated that obesity-related hypoventilation or apnea is closely associated with leptin signaling pathways." (PMID 29636698, 2018). "In univariate analyses leptin levels were positively associated with injury duration, BMI, fat mass, total lean mass, IL-6, and obesity status and were negatively associated with adiponectin and sarcopenia status." (PMID 29949600, 2018). "Increased leptin is directly associated with obesity and is suspected to be involved in reorganizing the cytoskeleton of nucleus pulposus cells, thereby altering disc organization and structure." (PMID 29483883, 2018). "Leptin resistance has been shown to be associated with obesity in humans, and obese individuals have higher levels of leptin as compared to healthy individuals." (PMID 30254821, 2018). "In contrast, common polygenetic obesity is associated with increased leptin levels and treatment with additional leptin has limited efficacy to lower body-weight under these circumstances." (PMID 29748097, 2018). "Among them, adiponectin and leptin are the most important and are therefore the focus here in discussing obesity-associated PC." (PMID 30567565, 2018). "The most common and treatable form of monogenic obesity is due to mutations in the LEP gene manifesting as hyperphagia and rapid weight gain starting from early infancy." (PMID 29217499, 2018). "It is well accepted that fat mass determines plasma leptin concentrations and that excessive adiposity is associated with elevated circulating leptin levels; this plays a key role in obesity‐induced oxidative stress (Milagro, Campion & Martinez, 2006)." (PMID 29424490, 2018). "Leptin’s levels are increased in obesity that is pandemic and strongly linked to incidence of PC and other cancers." (PMID 30004402, 2018). "Obesity-related leptin resistance is associated with impairments in hippocampal-dependent learning and memory in rodents and in humans." (PMID 29860205, 2018). "Increases in the serum levels of leptin and oxidative stress, both of which are involved in obesity, also predicted the risk of HCC recurrence." (PMID 29581826, 2018). "Obesity-associated factors or adipokines, especially leptin and resistin, are purported to promote growth, survival, proliferation, and invasiveness of cancer cells." (PMID 29568521, 2018). "In view of intense hyperphagia followed by rapid weight gain, early age of onset, family history of EOO and low level of circulating leptin, a diagnosis of monogenic obesity due to LEP gene mutation was considered." (PMID 29217499, 2018). "In the literature, impaired leptin signaling is associated with over activation of the central EC system, contributing to obesity development." (PMID 30201891, 2018). "Traditionally, leptin-deficient (ob/ob) and leptin receptor-deficient (db/db) mice are used for studies on obesity but their utility in studying atherosclerosis is limited." (PMID 30914878, 2018). "Nonetheless, studies of other compounds with complementary or more powerful effects are necessary to combat metabolic diseases associated with leptin dysfunction, such as obesity." (PMID 30441779, 2018). "Leptin- or LepRb-deficient humans and rodent models display dramatic hyperphagia and reduced energy expenditure, leading to severe obesity." (PMID 29914853, 2018). "The disruption of LEPR and leptin deficiency results in severe early-onset hyperphagic obesity with rapid weight increase during the first few months of life." (PMID 30442103, 2018). "Taken together, these data demonstrate that Sel1L deficiency in POMC neurons leads to age-associated obesity due to overeating, partially due to impaired leptin response at a step downstream of pY-STAT3." (PMID 29457782, 2018).